C3orf70 (chromosome 3 open reading frame 70)
Description:
May play a role in neuronal and neurobehavioral development.
Tractability: No criterion of Open Targets' tractability assessment is met for any kind of drug.
Gene: Protein-coding gene on chromosome 3 (185,076,838 to 185,153,060, reverse strand). Ensembl gene ENSG00000187068.
Subcellular location (Human Protein Atlas): Cytosol
Gene Ontology:
Biological process: circadian behavior; nervous system development
Genetic constraint (gnomAD): Loss-of-function variants: 15 observed, 18.23 expected, observed/expected ratio (o/e) 0.82, 90% interval 0.55 to 1.27. The synonymous counts are far from expectation, so gnomAD's model fits this gene poorly and the ratio says little. Missense variants: 332 observed, 314.78 expected, observed/expected ratio (o/e) 1.05, 90% interval 0.96 to 1.15. Synonymous variants: 161 observed, 127.28 expected, observed/expected ratio (o/e) 1.26, 90% interval 1.11 to 1.44.
Homologues: Orthologues: chimpanzee C3H3orf70 (100% identical), macaque C2H3orf70 (99% identical), pig C3orf70 (98% identical), dog C3orf70 (96% identical), mouse 2510009E07Rik (93% identical), rat C11h3orf70 (92% identical), guinea pig C3orf70 (86% identical), tropical clawed frog c9h3orf70 (71% identical), zebrafish C9H3orf70 (62% identical), zebrafish C9H3orf70 (60% identical).
Diseases named in the same sentence as C3orf70 in open-access papers:
C3orf70 is named in the same sentence as 11 diseases in open-access papers, as found by Europe PMC text mining. Sharing a sentence is not in itself a finding about the gene and the disease. The quoted sentences say what the papers report.
cervical cancer (1 paper, 2021). A primary or metastatic malignant neoplasm involving the cervix. "The down-regulated C3orf70 expression is closely related with a poor prognosis of cervical cancer." (PMID 34221990, 2021).
insomnia (1 paper, 2019). A sleep disorder characterized by difficulty in falling asleep and/or remaining asleep. "Interestingly, genetic analyses have demonstrated that C3orf70 is associated with educational attainment, major depressive disorder, and insomnia." (PMID 31623237, 2019).
tumour (2 papers, 2019 to 2020).
cancer (1 paper, 2023). A tumor composed of atypical neoplastic, often pleomorphic cells that invade other tissues. "A search for novel genetic variants of C3orf70, C8orf33, C8orf76 and C8orf82 associated with systemic diseases, including cancers, is of practical interest for medical genomics." (PMID 37373333, 2023). "It is interesting to note that GA frequency is up to 6% in C3orf70, C8orf33, C8orf76 and C8orf82 genes according to the most affected cancer types." (PMID 37373333, 2023).
C3orf70 also shares sentences with these, for which no sentence is quoted: Alzheimer disease (1 paper); Anxiety (1); embryonic carcinoma (1); epilepsy (1); major depressive disorder (1); Obesity (1); schizophrenia (1).